GPRC5B (G protein-coupled receptor class C group 5 member B)
Description:
G protein-coupled receptor involved in the regulation of cell volume.
Synonyms: RAIG-2; RAIG2; MLC3
Tractability: Antibody: UniProt places it where antibodies can reach, with high confidence; UniProt predicts a signal peptide or a membrane-spanning region; its Gene Ontology location is reachable by antibodies, with medium confidence. PROTAC: ubiquitination databases record sites on it; its protein half-life has been measured.
Target class: Family C G protein-coupled receptor; Membrane receptor
Gene: Protein-coding gene on chromosome 16 (19,856,691 to 19,886,173, reverse strand). Ensembl gene ENSG00000167191.
Subcellular location: Cell membrane; Cytoplasmic vesicle membrane
Subcellular location (Human Protein Atlas): Vesicles; Nucleoli; Nucleoplasm
Gene Ontology:
Molecular function: protein binding; protein kinase activator activity; protein tyrosine kinase binding; G protein-coupled receptor binding; protein kinase binding; G protein-coupled receptor activity; protein kinase inhibitor activity
Biological process: cell volume homeostasis; intracellular signal transduction; G protein-coupled receptor signaling pathway
Cellular component: extracellular exosome; extracellular region; membrane raft; cell surface; plasma membrane; receptor complex; cytoplasmic vesicle membrane; membrane
Genetic constraint (gnomAD): Loss-of-function variants: 15 observed, 29.41 expected, observed/expected ratio (o/e) 0.51, 90% interval 0.34 to 0.79. The upper end of that interval is the gene's LOEUF score, 0.79, which puts it in group 3 of 6, group 1 being the genes least tolerant of losing a copy. Missense variants: 417 observed, 547.22 expected, observed/expected ratio (o/e) 0.76, 90% interval 0.7 to 0.83. Synonymous variants: 239 observed, 246.01 expected, observed/expected ratio (o/e) 0.97, 90% interval 0.87 to 1.08.
Homologues: Orthologues: chimpanzee GPRC5B (98% identical), macaque GPRC5B (97% identical), guinea pig GPRC5B (88% identical), pig GPRC5B (87% identical), dog GPRC5B (87% identical), rat Gprc5b (86% identical), mouse Gprc5b (84% identical), rabbit GPRC5B (79% identical), tropical clawed frog gprc5b (72% identical), zebrafish gprc5ba (47% identical), zebrafish gprc5bb (43% identical). Paralogues in human: GPRC5C (41% identical), GPRC5A (29% identical), GPRC5D (27% identical).
Diseases named in the same sentence as GPRC5B in open-access papers:
GPRC5B is named in the same sentence as 32 diseases in open-access papers, as found by Europe PMC text mining. Sharing a sentence is not in itself a finding about the gene and the disease. The quoted sentences say what the papers report.
Obesity (16 papers, 2013 to 2025). Accumulation of substantial excess body fat. "Constitutive deletion of the gene encoding GPRC5B, Gprc5b, results in mice in altered neurogenesis and behavioral abnormalities; in addition, GPRC5B-KOs are protected from diet-induced obesity." (PMID 40906536, 2025). "Previous studies suggested that Gprc5b expression is upregulated during type 2 diabetes, which led us to investigate the role of GPRC5B in mice with diet-induced obesity, a model that is associated with development of insulin resistance and type 2 diabetes." (PMID 40906536, 2025). "In humans, GPRC5B is expressed ubiquitously and a genome-wide association study has identified GPRC5B as a genetic locus for obesity predisposition, probably due to copy-number variance." (PMID 36766718, 2023). "Consistent with the growth restriction and failure to thrive which we report here, prior studies also showed that loss of Gprc5b protected mice from diet-induced obesity and insulin resistance due to decreased inflammation in white adipose tissue." (PMID 35628521, 2022). "A 45-kb deletion near NEGR1 gene and a 50-kb deletion upstream of GPRC5B gene previously associated to obesity and body mass index were also identified." (PMID 23844243, 2013). "In addition, reduced obesity and obesity-associated inflammation have been described in Gprc5b knockout mice." (PMID 39920161, 2025). "Recently, aberrant expression of GPRC5B was identified to be an obesity risk factor." (PMID 28045997, 2017). "Recently, aberrant expression of GPRC5B was identified as an obesity risk factor." (PMID 26193363, 2015). "Furthermore, some studies indicated that GPRC5B might be involved in the regulation of obesity-associated inflammatory response and macrophage infiltration." (PMID 35046932, 2021). "The regions showing association with obesity‐related phenotypes are located at 11q11 (OR4P4, OR4S2, OR4C6), 1p21.1 (AMΥ1), 10q11.22 (NPY4R), 10q26.3 (CYP2E1), 16q12.2 (FTO), 16p12.3 (GPRC5b), and 4q25 and have been associated with adult obesity as well." (PMID 41082226, 2025). "Taken together, GPRC5B helps to maintain mature β cell function in obesity through cAMP/CREB-dependent regulation of MafA expression." (PMID 40906536, 2025). "GPRC5B knockout in mice reduced fat production and prevented diet-induced obesity and insulin resistance." (PMID 38824596, 2024). "GPRC5B has previously been shown to activate obesity-induced inflammatory signaling in adipocytes and Gprc5b-/- mice are protected from diet-induced obesity and insulin resistance." (PMID 36766718, 2023). "Firstly, the sample size was insufficient to detect associations of obesity with low frequency alleles (1p31.1/NEGR1, 10q11.22/GPRC5B, and 16p12.3/NPY4R), although it was sufficient to find associations with 11q11/OR4P4/OR4S2/OR4C6, and 1p21.1/AMY1 CNs." (PMID 30388780, 2018). "This function seems to be conserved during evolution, because knockout of the mice homologue GPRC5B protected the mice from obesity resulting from a high-fat diet." (PMID 26193363, 2015). "In global GPRC5B-KO mice, circulating insulin levels were reduced especially in diet-induced obesity, but since KOs also showed a lean phenotype with reduced insulin resistance and lower obesity-associated inflammation, these changes might have been secondary." (PMID 40906536, 2025). "So far, the function of GPRC5B in metabolic processes has mainly been studied in the context of adipose tissue biology; global GPRC5B-KO mice were protected from diet-induced obesity and insulin resistance, and metabolic-induced inflammation in their white adipose tissue was reduced." (PMID 40906536, 2025). "A recent study reported that GPRC5B might be a control point in adipose signaling systems, linking diet-induced obesity to type-2 diabetes." (PMID 26161641, 2015).
Obesity (continued). "Interestingly, MafA levels are — despite reduced CREB phosphorylation — not yet significantly changed in lean mice, which might indicate that GPRC5B-dependent cAMP/CREB regulation becomes more relevant for MafA regulation during obesity development." (PMID 40906536, 2025). "Orphan receptor GPRC5B maintains mature β-cell function in obesity via cAMP/CREB-dependent MafA regulation; β-cell-specific GPRC5B-knockout mice have reduced insulin secretion and develop a prediabetic condition." (PMID 40906536, 2025).
Insulin resistance (7 papers, 2019 to 2025). Increased resistance towards insulin, that is, diminished effectiveness of insulin in reducing blood glucose levels. "GPRC5B, an obesity-related membrane protein implicated in insulin resistance, may contribute to the metabolic disturbances characteristic of type 2 diabetes mellitus (T2DM), including increased adiposity, impaired insulin secretion, and glucose intolerance." (PMID 40864777, 2025). "Recent work revealed that SMS2-generated diacylglycerol at the plasma membrane is critical for the development of insulin resistance and controlled by GPRC5B-mediated SMS2 phosphorylation." (PMID 30779713, 2019). "Furthermore, GPRC5B facilitates Fyn-dependent phosphorylation of sphingomyelin synthase 2 (SMS2), which activates the diacylglycerol/protein kinase C/c-Jun N-terminal kinase (DAG/PKC/JNK) signaling cascade, a key pathway in the pathogenesis of insulin resistance." (PMID 40864777, 2025).
type 2 diabetes (4 papers, 2015 to 2025). "In this context, it is interesting to note that GPRC5B expression is increased in islets of patients with type 2 diabetes." (PMID 40906536, 2025). "Previous expression studies suggested that orphan GPCR GPRC5B is upregulated in pancreatic islets of patients with type 2 diabetes, but the in vivo function of GPRC5B in β cells has not been thoroughly addressed." (PMID 40906536, 2025).
astrocytoma (2 papers, 2010 to 2025). "Patient-derived lymphocytes exhibited elevated GPRC5B expression, and overexpression in U251 astrocytoma cells demonstrated increased volume-regulated anion channel currents, an effect preserved in GPRC5B variants harboring these mutations." (PMID 41314544, 2025).
breast carcinoma (2 papers, 2018 to 2023). "A whole transcriptomics analysis has revealed that GPRC5B is elevated in immuno-activated breast cancer cells, while apigenin induces a 94% reduction in GPRC5B expression." (PMID 36925638, 2023). "We detected two receptors uniquely expressed in all breast cancer cell lines but not in control cells: GPRC5B (a Class-C orphan receptor, ΔCt = 17.8) and TBXA2R (thromboxane A2 receptor, ΔCt = 19.4)." (PMID 29872392, 2018).
depression (2 papers, 2013 to 2022). "GPR37 and GPRC5B are both implicated in Parkinson's disease, which has depression as one premorbid indicator, possibly concomitant with brain neurodegenerative processes." (PMID 24391664, 2013). "Furthermore, transcriptional analysis in post-mortem brain from patients suggested an involvement of GPRC5B in signaling pathways leading to bipolar disorders (BPD) and major depressive disorders (MDD)." (PMID 35812210, 2022).
diabetes (2 papers, 2017 to 2024). "NBXH treatment can downregulate gprc5b expression, which is beneficial to prevent TB with diabetes." (PMID 39364045, 2024). "We have also identified that several well-characterised GPCRs (CASR, GPRC5B, GPR119, F2RL1), which are either current drug targets or under evaluation as potential diabetes therapeutic targets, are highly expressed in both human and mouse islets." (PMID 28422162, 2017).
attention deficit-hyperactivity disorder (1 paper, 2022). A disorder characterized by a marked pattern of inattention and/or hyperactivity-impulsivity that is inconsistent with developmental level and clearly interferes with functioning in at least two settings (e.g. at home and at school). "Finally, genome-wide association studies (GWAS) sorted out that intronic regions of GPRC5B may be involved in the etiology of attention deficit hyperactivity disorder (ADHD)." (PMID 35812210, 2022).
bipolar disorder (1 paper, 2022). A disorder of the brain that causes unusual shifts in mood, energy, activity levels and the ability to carry out day-to-day tasks. "Indeed, GPRC5B expression is reduced in patients diagnosed with major depressive disease, while GPRC5B expression is increased in several patients with bipolar disorder." (PMID 35159337, 2022).
colitis (1 paper, 2025). Inflammation of the colon. "Since LysM-Cre mediates recombination also in neutrophilic granulocytes, a cell population that contributes to the pathogenesis of colitis and cardiac remodeling, we analyzed consequences of GPRC5B deficiency in these cells." (PMID 39920161, 2025).
colon adenocarcinoma (1 paper, 2021). "GPRC5B was significantly downregulated in colon adenocarcinoma (COAD) as seen in 28 patient samples." (PMID 35046932, 2021).
colon cancer (1 paper, 2021). "In this study, we constructed a 6-gene signature (ITLN1, HOXD9, TSPAN11, GPRC5B, TIMP1 and CXCL13) prognostic stratification system based on the colon cancer invasion-related genes, and evaluated the stability and accuracy of the model." (PMID 33579281, 2021).
Glucose intolerance (1 paper, 2025). Glucose intolerance (GI) can be defined as dysglycemia that comprises both prediabetes and diabetes. "Taken together, our data show that GPRC5B helps to maintain a mature β cell phenotype by regulating the cAMP/CREB/MafA pathway and that genetic inactivation of this receptor leads to reduced insulin secretion and glucose intolerance in HFD-fed mice." (PMID 40906536, 2025).
hydrops fetalis (1 paper, 2022). Hydrops fetalis is a severe and challenging fetal condition usually defined as the excessive accumulation of fetal fluid within the fetal extravascular compartments and body cavities that manifests as edema, pleural and pericardial effusion and ascites. "Morphant gprc5b zebrafish exhibited failure of thoracic duct formation, and Gprc5b−/− mice suffered from embryonic hydrops fetalis and hemorrhage associated with subcutaneous edema and blood-filled lymphatic vessels." (PMID 35628521, 2022).
insulinoma (1 paper, 2025). "The same study showed reduced cytokine-induced cell death in cells isolated from Gprc5b-knockdown islets, whereas overexpression of GPRC5B in MIN6 insulinoma cells enhanced both proliferation and apoptosis." (PMID 40906536, 2025). "Finally, in vitro studies in MIN6 insulinoma cells suggested a role of GPRC5B in β cell proliferation and apoptosis." (PMID 40906536, 2025).
leukodystrophy (1 paper, 2025). Leukodystrophies are a group of rare, progressive, metabolic, genetic diseases that affect the brain, spinal cord and often the peripheral nerves. "We demonstrate that GPRC5B exhibits constitutive signaling activity and that leukodystrophy-associated GPRC5B mutations do not impair this activity but rather enhance receptor stability." (PMID 41314544, 2025).
mood disorder (1 paper, 2013). A cognitive disorder a disturbance in which the person's mood is hypothesized to be the main underlying feature. "Functional characterization of GPRC5B and GPR37 may provide new insights into the pathophysiology of mood disorder, and potential novel strategies for developing methods for diagnoses and treatment of the disorders." (PMID 24391664, 2013).
neuroblastoma (1 paper, 2010). Neuroblastoma (NB) is the most common solid, extracranial childhood tumor. "Overexpression of both Gprc5b variants stimulated neurite-like outgrowth in a neuroblastoma cell line." (PMID 20436672, 2010).
pancreatic diseases (1 paper, 2021). "Some of them were upregulated in patients with other pancreatic diseases, such as HBB, HBA1, and KRT16 proteins, while some were upregulated only in PC groups (i.e. ALIX, GPRC5B, SDCBP, and IST1), highlighting their potential diagnostic value." (PMID 34026608, 2021). "Four proteins were significantly higher in PC compared with other pancreatic diseases, including PDCD6IP (also known as ALIX), GPRC5B, SDCBP, and IST1." (PMID 34026608, 2021).
peritonitis (1 paper, 2025). Inflammation of the peritoneum (tissue that lines the abdominal wall and covers most of the organs in the abdomen). "Both resident peritoneal and bone marrow-derived macrophages from myeloid-specific GPRC5B-deficient mice show increased migration and phagocytosis, resulting in improved bacterial clearance in a peritonitis model." (PMID 39920161, 2025). "Taken together, GPRC5B-deficient RPM are characterized by increased migration and phagocytosis, resulting in improved bacterial clearance in a peritonitis model." (PMID 39920161, 2025).
cancer (5 papers, 2010 to 2026). A tumor composed of atypical neoplastic, often pleomorphic cells that invade other tissues. "Some studies have indicated the role of GPRC5B in cancer, while its specific molecular mechanisms remain largely unknown." (PMID 35046932, 2021). "Pan-cancer expression analysis results showed that ITLN1, TSPAN11, CXCL13, and GPRC5B were downregulated and TIMP1 was upregulated in most tumor samples, including COAD, which was consistent with the results of the TCGA and GEO cohorts." (PMID 33579281, 2021).
tumor (3 papers, 2011 to 2021). "We confirmed that GPRC5B was significantly correlated with tumor-infiltrating macrophages using four algorithms (EPIC, XCELL, TIMER, and MCP-counter)." (PMID 35046932, 2021). "Next, according to the integrated analysis of GPRC5B and tumor-infiltrating immune cells, we also showed that GPRC5B was significantly associated with macrophages." (PMID 35046932, 2021). "GPRC5B, correlated with tumor-infiltrating macrophages, is a potential key molecule affecting COAD prognosis." (PMID 35046932, 2021). "The interaction between GPRC5B and tumor-infiltrating macrophages could be a potential target for clinical therapy." (PMID 35046932, 2021). "Moreover, according to Timer 2.0 database, GPRC5B was identified as a differentially expressed gene in various tumor types, including COAD." (PMID 35046932, 2021). "With the knowledge that macrophages are important in COAD development and progression, we hypothesized that the interactions between GPRC5B and tumor-infiltrating macrophages, potentially type M2, might be important in COAD and further affect the prognosis of patients with COAD." (PMID 35046932, 2021). "GPRC5B was significantly downregulated in COAD patients, while its expression would increase with the increase in tumor stages." (PMID 35046932, 2021). "Tumor immune infiltration analysis results showed that TSPAN11, GPRC5B, TIMP1, and CXCL13 protein levels were significantly positively correlated with CD4+ T cells, macrophages, neutrophils, and dendritic cells." (PMID 33579281, 2021).
GPRC5B also shares sentences with these, for which no sentence is quoted: atherosclerosis (1 paper); bullous pemphigoid (1); cognitive decline (1); epidermolysis bullosa acquisita (1); Failure to thrive (1); hyperlipidemia (1); lymphatic disorders (1); megalencephalic leukoencephalopathy (1); Parkinson disease (1); triple-negative breast carcinoma (1).